CRP (C-reactive protein)
Diseases named in the same sentence as CRP in open-access papers (continued):
Sharing a sentence is not in itself a finding about the gene and the disease.
Sepsis (continued). "We also tested the ability for cell surface markers and CRP to predict MOF and sepsis within the complicated patient groups alone, which is likely to represent a realistic target patient group in whom clinicians would want to assess the risk of sepsis/MOF (e.g., SIRS vs. sepsis in the ICU)." (PMID 34065206, 2021). "The potential cause might be that the CRP level peaked within only 48 h and failed to reflect the terminal state of sepsis." (PMID 34722578, 2021). "Therefore, CRP can be used as an essential auxiliary index for the diagnosis of sepsis." (PMID 34233608, 2021). "Therefore, detecting CRP is of great significance for the early diagnosis of sepsis." (PMID 34281552, 2021). "The ratio of serum levels of CRP to albumin has been demonstrated to be a more accurate indicator than albumin and CRP levels alone for determining the prognosis of patients with various inflammatory diseases such as sepsis, cancer, acute pancreatitis, ulcerative colitis, and hepatitis B." (PMID 33453709, 2021). "However, there are few clinical studies on PCT and CRP to assess sepsis in critically ill patients." (PMID 34233608, 2021). "In the field of sepsis, active areas of investigation are the testing of sensitive and specific biomarkers of sepsis, with research into leukocyte biomarkers which may replace the currently used CRP and Procalcitonin measurements." (PMID 33923571, 2021). "The second hypothesis was that although the adjudicators were blinded to PCT and CRP results performed by protocol, they had access to PCT and CRP values obtained as standard of care, which may have contributed to an overestimation of the performance of these two sepsis biomarkers in our study." (PMID 34193208, 2021). "Taking into account that the difference in immune system maturity could be the origin of the heterogeneity of the immune response during sepsis, we also determined specific immune mediators (CRP and PCT) to have more elements for better prediction of sepsis development in preterm neonates." (PMID 33521320, 2021). "Our findings agree with results from a small case-control study in Egyptian children with sepsis (n = 40, mean age 6 years) and a large community-based study of children (n = 4274, mean age 9.9 years) in England, which reported that 25(OH)D levels increased with increasing levels of CRP and IL-6." (PMID 34011341, 2021). "Considering that previous studies always found the markers in combination outperforming either marker alone in terms of making predictions of patients' prognosis, we speculated CRP/Alb or PCT/Alb might be the valuable marker for predicting mortality in sepsis-induced AKI patients." (PMID 34141715, 2021). "IL-6, PCT and CRP at onset of sepsis were associated with various clinical measures of sepsis severity, such as need for inotropic support and mechanical ventilation, with IL-6 and PCT showing the strongest associations, with a higher discriminative value compared to CRP." (PMID 33407770, 2021). "Importantly, close associations between miR-381-3p and clinical parameters of sepsis patients (such as PCT, WBC, CRP, Scr, SOFA, and APACHE II) were clarified, in order to further propose the underlying possibility that miR-381-3p regulated the development of sepsis." (PMID 34784841, 2021). "This confirmed that increases of CRP may occur in different inflammatory conditions and are thus not specific for sepsis and slightly decreased the diagnostic performance of CRP when the test was applied only on sick dogs." (PMID 34072427, 2021). "We did not include procalcitonin, which may be a better prognostic marker of sepsis than CRP." (PMID 33585129, 2021). "At the preoperative time point, the predictors of sepsis were monocyte L-selectin, with an AUC of 0.761 (95%CI 0.632–0.891) p = 0.0003, neutrophil L-selectin with an AUC of 0.692 (95%CI 0.574–0.810) p = 0.007, and CRP with an AUC of 0.772 (95%CI 0.650–0.893) p = 0.0001." (PMID 34065206, 2021).
Sepsis (continued). "In addition, fetal infection may progress rapidly to sepsis (within 24 h of birth), which might occur before serum CRP elevation is detectable." (PMID 33211747, 2020). "The ROC curve analysis shows that TTP combined with IG%, IG#, or CRP can improve the discrimination efficiency of CoNS infection and peripheral toxemia as might be seen in sepsis/septicemia; however, IG% was completely consistent with an improved efficacy of IG#." (PMID 33463771, 2020). "Lnc‐MALAT1 was positively correlated with Scr (r = .254, P < .001), CRP (r = .494, P < .001), TNF‐α (r = .387, P < .001), IL‐1β (r = .330, P < .001), IL‐6 (r = .431, P < .001), and IL‐8 (r = .420, P < .001), while negatively associated with albumin (r = −.153, P = .033) in sepsis patients." (PMID 32309886, 2020). "However, presepsin may still have an advantage over procalcitonin and CRP for early screening of sepsis." (PMID 33198109, 2020). "However, CRP was significantly higher in the sepsis group (P = 0.00)." (PMID 32750089, 2020). "Furthermore, these asplenic patients are at an increased risk of sepsis and thrombosis, which may explain the elevated WBC counts and serum CRP in the ACS group." (PMID 32051480, 2020). "Elevations in CRP may be predictive of mortality in pediatric severe sepsis and septic shock." (PMID 33340348, 2020). "Once established the negativity of the cultures and the absence of risk factors for early-onset sepsis, the CRP increase and the poor clinical conditions in the first day of life may be referred to the unlucky hemorrhagic event." (PMID 31068206, 2019). "Moreover, the CRP level within 48 h before treatment has been shown to potentially help in assessing the response of patients with sepsis to initiate antimicrobial therapy, and the CRP level at admission might serve as a useful marker of early infection." (PMID 31671729, 2019). "Moreover, owing to the hepatic provenience of CRP, in the case of severe liver failure, CRP levels may be falsely low and may rather reflect the degree of hepatic dysfunction than sepsis or inflammation, limiting its use in clinical routine." (PMID 31569348, 2019). "However, considering the cost factor, longer half-life and the statistically proven data of reliability of serial monitoring of CRP in resolution or worsening of sepsis, it can be adopted as "must do" investigation for patients admitted with sepsis and initiated on antibiotics." (PMID 31065202, 2019). "Furthermore, presepsin levels increase earlier in response to sepsis than either CRP or PCT." (PMID 31470804, 2019). "However, further studies are required to determine if different cut-off values of CRP at different timings during late-onset sepsis evaluation in VLBW infants could increase sensitivity." (PMID 29382319, 2018). "Hence, many studies have recently investigated whether the ratio of CRP to ALB can effectively reflect the prognosis of critically ill patients diagnosed with severe sepsis or septic shock." (PMID 29495423, 2018). "However, less is known about the CRP response of VLBW infants in late-onset sepsis." (PMID 29382319, 2018). "A further episode presented with K. pneumonia and E. coli with a CRP of 19.5 mg/dL; two more episodes of clinical sepsis without yield of a causative agent in conventional blood culture but positive PCR signal were caused by E. faecalis (CRP = 3.8 mg/dL) and S. aureus (CRP = 31.2 mg/dL)." (PMID 29117261, 2017). "Moreover, our results indicated that the largest ROCAUC of sCD14-ST was 0.953 with high sensitivity (93.8%) and specificity (77.1%) and suggested that sCD14-ST had a certain advantage in the early diagnosis of pediatric sepsis and higher sensitivity than CRP or TBIL." (PMID 28758124, 2017). "Moreover, MG outmatched the established markers of inflammation and infection, such as procalcitonin (PCT), C-reactive protein (CRP), soluble cluster of differentiation (CD) 14 subtype and IL-6, with regards to early and effective detection of sepsis in that study." (PMID 28304355, 2017).
Sepsis (continued). "Non-specific dynamics of CRP don’t support its use as diagnostic biomarker of sepsis." (PMID 28235076, 2017). "Nevertheless, the lack of association in the sepsis cohort between these meausures and an established biomarker (CRP) is a limitation of the present study and would need to be investigated in future, prospective studies evaluating these biomarkers for the early detection of children with sepsis." (PMID 27089280, 2016). "Additionally, we didn’t find any relationship between WBCC and each of CRP, sepsis and mortality." (PMID 26863002, 2016). "Serum procalcitonin and C-reactive protein appear to be useful to rule out infection or monitor therapy; however, the diagnostic and prognostic value of mediators for complications/outcomes of sepsis or injury remains to be established." (PMID 26502877, 2015). "Similarly, PCT the most widely utilized “new generation” biomarker that, especially in combination with additional inflammatory markers such as IL6 and CRP, is reported in some studies as having a good predictive value for sepsis, was temporarily increased after surgery in both groups." (PMID 26263001, 2015). "We investigated the use of the CRP/albumin ratio as an independent predictor of mortality in these patients where we hypothesized that this ratio could be used as an independent predictor of mortality in patients with severe sepsis or septic shock." (PMID 26158725, 2015). "Furthermore, some CRP levels may have been falsely low because they were obtained too early before they started to rise around 4–6 h after sepsis onset." (PMID 26259626, 2015). "An increase in soluble TREM-1 (sTREM-1) has been described for sepsis patients, where levels could predict survival rates in sepsis better than PCT or CRP, were a good assessment for the prognosis of positive blood cultures and noted as reliable biomarker for sepsis." (PMID 26263001, 2015). "Thus, we chose peak levels of these biochemical markers within two days as the initial baseline because early peak levels of PCT or CRP may approximately represent clinical deterioration onset and sepsis severity." (PMID 26367532, 2015). "In this study, we investigated whether macrophage-related biomarkers that reflect infectious inflammation in sepsis could be used diagnostic and prognostic and whether they are superior to the non-specific CRP." (PMID 24637679, 2014). "However, the levels of CRP fail to predict infection or sepsis in patients with major burns." (PMID 25489947, 2014). "Therefore, CRP and serum albumin levels should diverge during sepsis." (PMID 23555017, 2013). "However, SAA rises earlier and more sharply than CRP, especially during the first 24 h after sepsis onset, and it has showed a moderate accuracy at 8–96 h after the first suspicion of sepsis in our meta-analysis, which means that SAA is useful in the diagnosis of NS." (PMID 23984377, 2013). "CRP may be the link between inflammation and coagulation in sepsis." (PMID 24286072, 2013). "Notably, impedance aggregometry findings using collagen as the activator proved to be a better biomarker for both diagnosis of severe sepsis in critical illness and survival of severe sepsis than procalcitonin, interleukin 6, C-reactive protein and platelet count." (PMID 23088388, 2012). "In both univariate and multivariate analyses (including procalcitonin, IL6, C-reactive protein and platelet count) impedance aggregometry using collagen as the activator proved to be the best and an independent predictor for the diagnosis and prognosis of severe sepsis in critical illness." (PMID 23088388, 2012). "However, the diagnostic value of suPAR in sepsis has not been well defined, especially compared to other more established biomarkers, such as C-reactive protein (CRP) and procalcitonin (PCT)." (PMID 22221662, 2012).
Sepsis (continued). "In neonatal sepsis, a single CRP value was found to be a poor predictor of sepsis, whereas serial CRP measurements were good predictors of late-onset sepsis (LOS) in very-low-birth-weight neonates, whether performed as single tests or in combination with tests of the interleukin-6 (IL-6) level." (PMID 22943554, 2012). "However, CRP plasma concentrations increase as much as 1000-fold under inflammatory conditions, irrespective whether of bacterial (sepsis) or sterile (sepsis-like) origin." (PMID 22577258, 2012). "Procalcitonin (PCT) may have advantages over CRP as a marker for inflammation or sepsis." (PMID 23272177, 2012). "Moreover, CRP is elevated only in a minority of infants affected by fungi-related sepsis." (PMID 21765851, 2011). "Furthermore, LBP and CRP plasma levels have quite the same predictive value and are neither suitable to monitor resolution of sepsis nor sufficiently reliable to detect a recurrent infection during the first 14 days of sepsis in adult postoperative patients." (PMID 21901123, 2011). "Furthermore, comparison of thromboelastometry findings with the conventional biomarkers procalcitonin, interleukin 6, and C-reactive protein demonstrates a superior accuracy of the thromboelastometry lysis index in identifying patients with severe sepsis in critically ill patients." (PMID 20929576, 2010). "Therefore, if no pathogenic bacterial agent is detected, the diagnosis of sepsis is based on the development of clinical signs only, often in combination with a rise in CRP." (PMID 19152691, 2009). "Although the performance of CRP was similar to that of PCT in predicting SBI, the rapid kinetics of PCT compared to CRP make it more likely to detect sepsis early, and could be used to initiate antibiotics early in children at risk of sepsis." (PMID 19675669, 2009). "In this study, we tested the hypothesis that CRP is associated with hypofibrinolysis in intensive care patients with and without sepsis." (PMID 15456513, 2004). "Although not as good as procalcitonin (PCT) or C‐reactive protein (CRP), exosomal Rmrp still showed good diagnostic performance for sepsis, suggesting that exosomal Rmrp may serve as a potential biomarker for sepsis diagnosis." (PMID 41178622, 2026). "POC bio-ADM levels were analyzed using univariate and multivariable binary logistic regression and compared to established sepsis biomarkers (PCT, CRP, lactate)." (PMID 41764483, 2026). "A small prospective study measured LBP and other sepsis biomarkers, including PCT and CRP, on admission in 102 adult patients presenting with suspected infection." (PMID 41597433, 2026). "Outcomes included changes in the modified Töllner score, Sepsis Prediction Score (SPS), and serum CRP." (PMID 42116025, 2026). "C-reactive protein (CRP) and procalcitonin (PCT) are the most widely used laboratory biomarkers for the diagnosis and monitoring of sepsis in clinical practice." (PMID 41597433, 2026). "Compared with ICU control patients, patients with sepsis had a higher SOFA score, with higher C-reactive protein and creatinine levels and lower platelets, hemoglobin, and MAP levels." (PMID 41035436, 2026). "For diagnosis of sepsis, HR, WBC, CRP, PCT, and lactate were used in addition to the physicians’ clinical judgment." (PMID 39857101, 2025). "It is also true, however, that all these studies mainly assessed CRP/Alb in ICU, sepsis, or cancer patients." (PMID 40573094, 2025). "The Sepsis group exhibited significantly increased NLR, PLR, and CRP levels compared to the Control group (p < 0.05)." (PMID 41196905, 2025). "C-reactive protein (CRP) and procalcitonin (PCT) have been studied extensively regarding the diagnosis and prognosis of sepsis and compared to the performance of other biomarkers." (PMID 40598497, 2025). "Presepsin (sCD14-ST) has recently emerged as a promising biomarker for the early diagnosis of sepsis, outperforming procalcitonin (PCT) and C-reactive protein (CRP) in some studies." (PMID 40804836, 2025).
Sepsis (continued). "Although CRP, PCT, and IL-6 are all established biomarkers in the diagnosis and management of sepsis, our study was limited by the availability of complete PCT and IL-6 data for all patients in our cohort." (PMID 40568199, 2025). "C-Reactive Protein (CRP) serves as a marker of inflammation or infection, aiding in the diagnosis of bacterial infections, sepsis, or inflammatory conditions." (PMID 40722084, 2025). "IL-6 and CRP levels were concurrently elevated and significantly elevated during the initial phase of DKA with sepsis, followed by a significant decrease after DKA improvement." (PMID 39946377, 2025). "The use of melatonin as an adjunctive therapy has significantly reduced C-Reactive Protein (CRP) and improved clinical status in neonates with sepsis." (PMID 40187234, 2025). "In all patients, the discriminative performance of MDW for predicting sepsis appeared superior to that of WBC count, NLR, and PLR; slightly exceeded that of CRP; and was comparable to that of PCT according to Sepsis-3 criteria." (PMID 41303127, 2025). "C-reactive protein (CRP) and procalcitonin (PCT) have emerged as valuable biomarkers for recognizing infectious inflammation and are widely utilized in sepsis diagnosis." (PMID 40687411, 2025). "IL-6 responds faster to infections than CRP and PCT, cementing its status as a key early indicator for sepsis." (PMID 41011807, 2025). "The sepsis group possessed elevated APACHE II and SOFA scores, and serum Lac, CRP, and PCT levels, and lower 25(OH)D levels versus the control group (P < 0.05)." (PMID 40370697, 2025). "Neutrophil CD64, when integrated with CRP and SOFA scores, attains an accuracy of 0.93 in forecasting sepsis mortality." (PMID 41341291, 2025). "Compared to C-reactive protein (CRP) and procalcitonin (PCT), IL-6 performs better for early sepsis diagnosis." (PMID 39857702, 2025). "CRP: C-reactive protein; EOS: early-onset sepsis; FBC: full blood count; IL-6: interleukin-6; LOS: late-onset sepsis; PCT: procalcitonin; POC: point-of-care; VLBW: very low birth weight; WBC: white blood cell count." (PMID 40970024, 2025). "MIS-C cases had a statistically higher IQR for CRP (13.8 mg/dL, IQR 7.5–21.2) than all other conditions except sepsis (10.0 mg/dL, IQR 4.2–21.8)." (PMID 41341432, 2025). "Traditional biomarkers such as C-reactive protein (CRP) and procalcitonin (PCT) have been widely used for diagnosing and monitoring sepsis; however, their clinical performance remains limited." (PMID 41301539, 2025). "C-reactive protein (CRP) and procalcitonin (PCT) are well-established biomarkers used to detect infections and sepsis." (PMID 41303127, 2025). "The peripheral blood inflammatory markers in patients with sepsis are the primary outcome measures of this study, including IL-6, TNF-α, and CRP." (PMID 41195185, 2025). "Although various biomarkers such as C-reactive protein (CRP), white blood cell count (WBC), procalcitonin (PCT) levels, platelet count, and serum lactate have been proposed for early sepsis prediction, their utility in clinical practice remains limited." (PMID 41393148, 2025). "In patients with initial signs of infection, PCT demonstrated the highest AUC for sepsis discrimination based on Sepsis-3 criteria (AUC 0.868), followed by MDW (0.855) and CRP (0.747)." (PMID 41303127, 2025). "Two analyses were conducted, the first estimating the cost per quality-adjusted life year (QALY) of the ADAPT-Sepsis study, which recruited 2760 patients randomized to a daily PCT-guided protocol, a daily C-reactive protein-guided protocol and standard care." (PMID 41316366, 2025). "Our findings revealed that NRBC counts, when analyzed alongside CRP and PCT levels, are valuable biomarkers for distinguishing between sepsis and septic shock." (PMID 40895306, 2025). "In immunodeficient patients, male patients had higher odds of developing sepsis, post-operative bleeding, post-operative infection, ESR/CRP elevation and wound dehiscence in silicone-treated patients." (PMID 41001471, 2025).